CD47 (CD47 molecule)
Diseases named in the same sentence as CD47 in open-access papers (continued):
Sharing a sentence is not in itself a finding about the gene and the disease.
prostate carcinoma (continued). "To determine if low CD47 activities influence the interaction between macrophages and cancer cells, we conducted phagocytosis assays with prostate cancer cell lines expressing different CD47 levels." (PMID 37848444, 2023). "Disruption of CD47 in PC3 prostate cancer cells similarly decreased SLFN11 expression and was associated with a CD47-dependent decrease in acetylation and increased methylation of histone H3 in the SLFN11 promoter region." (PMID 33925464, 2021). "Consistent with the drug screening data, ChIP data identified CD47-dependent regulation of histone modification in the SLFN11 promoter in prostate cancer cells." (PMID 31632920, 2019). "We further analyzed TCGA prostate cancer data to evaluate a potential role of CD47 in these two mechanisms for regulating SLFN11 transcription." (PMID 31632920, 2019). "A weaker negative correlation between CD47 mRNA expression and SLFN11 promoter methylation (p = 4.6 × 10−19) suggested that the regulation of SLFN11 expression in human prostate cancers by CD47 is mediated in part by this mechanism." (PMID 31632920, 2019). "The positive regulation of SLFN11 expression by CD47 extends to prostate cancer cells, and correlative data in human tumors extends this relationship to a subset of human cancers." (PMID 31632920, 2019). "In this study, we investigated the effect of overexpressing murine CD47 (mCD47) in the commonly used PC-3 human prostate cancer cell line on its metastatic potential in murine models." (PMID 26674012, 2015). "We investigated the effect of overexpressing murine CD47 (mCD47) in PC-3 cells, a commonly used human prostate cancer line, on the metastatic potential in three mouse strains with different genetic background and varying degrees of immunodeficiency." (PMID 26674012, 2015). "Furthermore, the interplay between IL-8/CXCR2 signalling, CD47 regulation, and macrophage infiltration has significant clinical implications in prostate cancer." (PMID 41163221, 2025). "Importantly, our findings reveal that IL-8/CXCR2 signalling regulates both the expression and membrane localization of CD47 in prostate cancer cells through palmitoylation, a lipid modification process." (PMID 41163221, 2025). "Moreover, macrophages were cocultured with mouse prostate cancer cell RM-1 blocked by CD47 antibody to observe the changes in phagocytosis efficiency in vitro." (PMID 37719086, 2023). "The relationship among CD47 and prostate cancer was further examined using the CancerSEA database." (PMID 37719086, 2023). "This indicates that CD47 expression level is high in malignant prostate cancer cells." (PMID 37719086, 2023). "We discovered that CD47 has high levels in prostate carcinoma and that it is positively connected with prostate cancer invasion, angiogenesis, resting, and proliferation and negatively correlated with DNA repair based on our examination of data from the GEPIA and CancerSEA databases." (PMID 37719086, 2023). "Therefore, a novel approach for potential immunotherapy may be provided by investigating the relationship among CD47 and the infiltration of immune cells in the prostate carcinoma." (PMID 37719086, 2023). "Therefore, this study used GEPIA to examine the variation in CD47 expression among carcinoma and normal tissues, TISCH and TIMER databases to explore the connection among CD47 and prostate cancer immunoinfiltrating cells, and in vitro phagocytosis experiments were conducted to block CD47 signals." (PMID 37719086, 2023). "Therefore, CD47 might be crucial in the immunoinfiltration of prostate cancer microenvironment, which will provide ideas for the potential function of CD47 in the immunotherapy of prostate cancer." (PMID 37719086, 2023). "Therefore, the elevated level of CD47 may promote the immune escape of prostate cancer cells, thus affecting the prognosis." (PMID 37719086, 2023). "Furthermore, the function of CD47 in prostate carcinoma was assessed by CancerSEA." (PMID 37719086, 2023).
prostate carcinoma (continued). "However, there is minimal information available about CD47's role in prostate cancer TME." (PMID 37719086, 2023). "Moreover, CD47 regulates SLFN11 expression in prostate cancer through promotor methylation." (PMID 34571887, 2021). "Using the prostate cancer cell lines PC-3 and DU145 transfected with FLAG-tagged CD47, we used the acyl-biotinyl exchange (ABE) method with biotin-HPDP followed by streptavidin blotting to confirm CD47 palmitoylation." (PMID 41163221, 2025). "Therefore, CD47 could serve as a viable immunological candidate for prostate cancer." (PMID 37719086, 2023). "Therefore, prostate cancer may be treated with tumor treatments that target CD47." (PMID 37719086, 2023). "Therefore, CD47 may provide novel strategies for potential immunotherapy of prostate cancer." (PMID 37719086, 2023). "CD47, also known as the “do not eat me” signal, is elevated in advanced prostate cancer and is modulated by inflammatory changes in the tumour microenvironment (TME)." (PMID 41163221, 2025). "Moreover, knockdown of CD47 in prostate cancer PC3 cells reduces both SLFN11 mRNA and protein levels, indicating SLFN11 is a target of CD47 in prostate cancer cells." (PMID 34571887, 2021). "We chose the PC3 line to examine whether CD47 also regulates SLFN11 expression and sensitivity to genotoxic stress in prostate cancer cells." (PMID 31632920, 2019). "Further analysis of the TCGA data for prostate cancers showed a positive correlation between CD47 and SLFN11 mRNA expression in the tumors but not in normal prostate tissues." (PMID 31632920, 2019). "Thus, to test our hypothesis that CD47 deficiency in tumor endothelial cells may enhance angiogenesis, we first assessed the growth and central necrosis in the tumors developed in WT vs. CD47-deficient mice following subcutaneous injection of syngeneic RM1 prostate cancer cells." (PMID 27283989, 2017). "Thus, targeting CXCR2 could not only reverse CD47/SIRPα-mediated resistance to phagocytosis and suppress M2 macrophage polarization but also counteract NED in prostate cancer cells." (PMID 41163221, 2025). "In prostate cancer cells, the lack of CD47 or blocking TSP-1-CD47 signaling promotes angiogenesis and enhances vascular integrity, leading to accelerated tumor progression." (PMID 34195295, 2021).
viral infection (20 papers, 2013 to 2025). "We have applied short and long TCR-CD3 stimulation of CD47-sufficient and CD47-deficient CD8+ T cells in vitro and tested CD8+ T cell physiology utilizing in vivo viral infection as well as tumor implantation models in CD47-sufficient and CD47-deficient mice." (PMID 36105746, 2022). "In this study, we investigate whether CD47 modulation by HIV-1 Vpu might promote the susceptibility of macrophages to viral infection via phagocytosis of infected CD4+ T cells." (PMID 34425695, 2021). "In the present study, immune-related markers were detected in H101-treated cells, and the results demonstrated that viral infection resulted in the downregulation of CD47 in infected cancer cells, which promoted THP-1 cell-induced phagocytosis of cancer cells." (PMID 40296909, 2025). "Fluorescence-activated cell sorting (FACS) analysis further confirmed the presence of CD47 protein on the cell surface of HNECs, with increased expression observed during viral infection." (PMID 38693120, 2024). "Subsequent to viral infection, ZO-1 abundance decreased, and its cellular connections were disrupted, while CD47 exhibited increased expression in both HNECs and HBECs." (PMID 38693120, 2024). "Immune cells from CD47‐nul mice showed loss of CD8+ T‐cell‐stimulated effector function and reduced natural killer (NK) cell control of viral infection, inferring that CD47 adds to immune cell capacity." (PMID 38362603, 2024). "It’s important to note that while CD47 induction by viral infection is specific to ciliated cells, not all ciliated cells were infected." (PMID 38693120, 2024). "The upregulation of CD47 in response to viral infections other than influenza has been documented in previous studies." (PMID 38693120, 2024). "We observed an increase in CD47 expression following viral infection, and this effect was replicated in HBECs treated with recombinant human IFN-β and IFN-λ1." (PMID 38693120, 2024). "Concerning this matter, it has also been shown that viral infection improves maturation of antigen presenting cells, leading to the idea of combining OVs with inhibitors of CD47." (PMID 38357194, 2024). "Through the validation process, we uncovered that CD47 induced by viral infection was not only detected in the colonization site (nasal epithelium) but also at the site of infection (bronchial epithelium)." (PMID 38693120, 2024). "Our RNAseq analysis of mouse CD8 T cells identified 199 CD47-dependent genes that are involved in CD8 cell responses to viral infection in mice." (PMID 36768931, 2023). "CD47 is a leukocyte surface antigen, which has been shown to be upregulated after a viral infection, including SARS-CoV-2 infection, as a host response to the infection." (PMID 33663372, 2021). "SIRPA interaction with CD47 on target cells decreases phagocytosis by about 50%, which is similar to its effect on virus infection." (PMID 34097709, 2021). "CD47 is upregulated by different cells upon chronic infection, notably viral infection, and tumor cells." (PMID 34925315, 2021). "Disruption of CD47 interaction on T cells has been shown to increase T cells response in both tumor and viral infection." (PMID 32882841, 2020). "In our recent study we shows that the blockade of CD47 using the anti-CD47 antibody increases the activation and effector function of macrophages, dendritic cells and T cells during viral infection." (PMID 32882841, 2020). "Our data supports roles for CD47 in NK cell precursor maturation and effector function in response to both acute and chronic viral infection." (PMID 30643501, 2018). "The present data identify roles for CD47 in murine NK cell homeostasis and function in viral infection that extend beyond the passive role of CD47 as a don't eat me signal." (PMID 30643501, 2018). "In summary, our studies identify important roles of CD47 in regulating NK cell homeostasis, proliferation, and responses to viral infection." (PMID 30643501, 2018).
viral infection (continued). "CEACAM1 and CD47 have previously been identified in the host cell response to viral infection and we have confirmed this observation with regard to HPIV3." (PMID 23742656, 2013). "Although NDV selectively infects and lyses tumor cells, viral infection unintentionally elevates tumor-cell CD47 expression—a “don’t-eat-me” signal that could mask the full immunostimulatory potential of NDV." (PMID 41322194, 2025). "Furthermore, our research has shown that inhibiting the upregulated airway epithelial CD47 during viral infection can mitigate the detrimental consequences of subsequent bacterial infection." (PMID 38693120, 2024). "Furthermore, the expression of the ‘eat-me’-signal calreticulin (CALR) on the tumor surface and the ‘don’t-eat-me’-signal CD47 was assessed during viral infection." (PMID 38357194, 2024). "Additionally, the upregulation of ICAM-1 and CD47 at 24 hpi was blocked, confirming the involvement of the NF-κB pathway in mediating CD47 upregulation in airway epithelial cells during viral infection." (PMID 38693120, 2024). "Two potential explanations may account for the expression of CD47 on the surface of host epithelial cells in response to viral infection." (PMID 38693120, 2024). "While prior research has focused on CD47’s involvement in immune cell communication during bacterial infection, our findings emphasize a distinct aspect where CD47 expressed in epithelial cells during viral infection serves as an attachment site for secondary bacterial infection." (PMID 38693120, 2024). "Considering the increased expression of CD47 in the tracheal and lung epithelium and the decreased expression of ZO-1 in the lung lysates of C57BL/6 WT mice following infection with influenza virus, we subsequently investigated the pathophysiological role of viral infection-induced CD47." (PMID 38693120, 2024). "There is growing evidence that disrupting the CD47 and SIRPα interaction may also benefit antiviral immunity during viral infections." (PMID 35746616, 2022). "Similarly, the frequency of Ki67+ CD8+ T cells increased from 20% in uninfected to 80% in infected mice, suggesting extensive cell proliferation in both WT and Cd47−/− animals upon viral infection." (PMID 36105746, 2022). "Furthermore, proinflammatory cytokines released after viral infections can upregulate CD47 on uninfected DCs, thus bridging innate suppressive modulation with downstream adaptive immune responses." (PMID 35746616, 2022). "Therefore, the anti-CD47 antibody increases the activation of both innate and adaptive immune response in two distinct viral infections." (PMID 32882841, 2020). "During chronic Cl-13 LCMV infection, Cd47−/− mice had significantly higher virus titers in serum than WT mice on days 8 (1.9-fold more in Cd47−/− than WT) and 15 (2.2-fold more in Cd47−/− than WT), suggesting viral infection progressed relatively faster in Cd47−/− mice." (PMID 30643501, 2018). "The present data suggest that altered splenic NK cell numbers or activation could account for the latter data and extends the systemic effects of CD47 to splenic NK cells in the context of viral infection." (PMID 30643501, 2018). "The significant downregulation of interferon signature genes, such as Adar (DRADA), Ddx58 (RIG-I), Ddx60 (DDX60), Stat1 (STAT1), Ifih1 (MDA5), Trim25 (TRIM25), Irf7 (IRF7), and Irf9 (IRF9) in infected Cd47−/− NK cells is consistent with the impaired Cd47−/− NK cell response to viral infection." (PMID 30643501, 2018). "However, the specific role of viral infection-induced CD47 in the context of secondary bacterial infection remains unclear." (PMID 38693120, 2024). "To verify whether the mCD47nb-Fc proteins released by the oncolytic adenovirus vector have a high binding affinity to CD47 on tumors, we tested CD47 occupancy after viral infection by flow cytometry and found that oAd-mCD47nb-Fc could effectively block CD47 in contrast to its counterpart." (PMID 35837100, 2022).
viral infection (continued). "We now show that viral infection with XVir significantly increased both calreticulin (CALR) surface expression (‘eat-me’) and CD47 surface expression (‘don’t-eat-me’) on all assessed tumors cells." (PMID 38357194, 2024). "Next, we studied in detail the host-induced reaction to viral infection on a transcriptomic level, seeing that iPNs have an intrinsic expression of the core ISGs like ADAR, STAT1, STAT2, or CD47, which was confirmed with publicly available single-cell datasets." (PMID 39546567, 2024). "This increased APC activation status in absence of CD47-signaling amplifies T cell activation and cytotoxicity during viral infection." (PMID 32882841, 2020). "We previously developed triple knock-out C57BL/6 Rag-/-γc-/-CD47-/- mice reconstituted with a human immune system using the bone marrow, liver, thymus method (TKO-BLT mice) for use in studies with HIV-1 and other viral infections that have tropism for human hematopoietic cells." (PMID 36298826, 2022). "However, during viral infection, the expression of ISGs including DHX58, IFITM3, ISG15, and OASL was upregulated in the livers of WT mice, while Neurl3−/− livers expressed a higher level of proteins related to inflammatory response such as S100A9 and CD47." (PMID 35792897, 2022). "All these CD47-blocking antibodies (both mouse and humanized) unanimously show a similar immunological effect resulting in increased phagocytosis and activation of antigen presenting cells, increased proliferation and activation of cytotoxic CD8 T cells during tumor and viral infections." (PMID 32882841, 2020). "Moreover, CD47-SIRPα interaction has bidirectional negative effect on regulation of human T cells and DCs and it has been reported that T cell immune response was enhanced by interruption of CD47 in viral infection and tumor immunity." (PMID 34093583, 2021).
breast tumors (19 papers, 2014 to 2025). "In this study, public genomic data was used to identify genes highly expressed in breast tumors with elevated CD47 expression and analyzed the association between the presence of tumor immune infiltrates and the expression of the selected genes." (PMID 33917174, 2021). "Because CD47, the “don’t eat me” signal, is a target for many cancer types, including breast tumors, understanding the molecular events that increase CD47 expression is a clinical need." (PMID 37190208, 2023). "Recent investigations have noted that HIF-1α can directly bind to its promoter to regulate the transcription of CD47 gene, and inhibition of CD47 increases the phagocytic ability of macrophages against breast tumor cells." (PMID 33422072, 2021). "Expression of both CD47 and HER2 is enhanced in irradiated BC cells, in RT-treated mouse syngeneic breast tumors, and in BC patients with recurrent diseases associated with a poor prognosis." (PMID 32929084, 2020). "In contrast to HER2 but consistent with our in vitro data, EGFR protein expression in breast tumors positively correlated with CD47 mRNA expression (p= 0.009)." (PMID 26840086, 2016). "Expression of CD47 (using the same IRS system) was comparably rare in hormone receptor positive breast tumors, representing only 5% of cases, (13/243 patients)." (PMID 25230070, 2014). "Interestingly, The CD47 level in primary breast tumours was significantly positive correlation with miR‐708 expression and patients’ poor survival." (PMID 31273952, 2019). "Notably, radiotherapy increased the rate of macrophage-mediated phagocytosis in the tumors treated with anti-CD47 antibodies in combination with Herceptin or single anti-CD47 antibodies compared to radiotherapy applied alone in the orthotopic breast tumor models." (PMID 36900399, 2023). "The 3rd generation 3D breast tumor spheroids displayed a stemness phenotype, as assessed by the methylcellulose clonogenic assay, riboflavin uptake, HIF-2α and CD47, CD44, CD24, and CD133 CSC marker expression." (PMID 34205080, 2021). "The radioresistant 4T1/C2 cells were then genetically edited by CRISPR technology to establish cells with CD47−/−, HER2−/−, or CD47−/−/HER2−/− status that were then used to create the syngeneic mouse orthotopic breast tumors." (PMID 32929084, 2020). "Local breast tumor radiation with a single dose 5 Gy delivered on day 9 further synergized the inhibition on CD47−/−/HER2−/− tumors, although again, the CD47−/− and HER2−/− tumors also generated an intermediate response compared to radiation alone." (PMID 32929084, 2020). "Using the mouse syngeneic mouse breast tumors with CD47−/−/HER2−/− status, we demonstrate an enhanced tumor inhibition by radiation combined with dual CD47 and HER2." (PMID 32929084, 2020). "Recent studies also demonstrated that CD47 transcription is regulated via HER2–NF-κB pathway, and antibody-mediated blockage of both CD47 and HER2 synergized with radiotherapy for the treatment of syngeneic mouse breast tumors." (PMID 36900399, 2023). "Raman images revealed effective targeting of our SERS nanoparticles to positively expressing CD47 breast tumors as opposed to normal adjacent tissue." (PMID 30463284, 2018). "Similarly a significant increase in CD47 expression was observed in three out of four PDX breast tumour samples (PDX1 showing the greatest effect) and one primary patient breast tumour after treating the cells with TNF-α for 24 h." (PMID 28378740, 2017). "The correlation between CD47 and EGFR expression in human breast tumors suggests that therapeutic CD47 antibodies may be effective against tumors with high EGFR expression when used alone or in combination with EGFR inhibitors." (PMID 26840086, 2016). "This ligand of CD47 induces PCD in vitro in breast tumors and leukemic cells." (PMID 25734483, 2015).